PDE4B (phosphodiesterase 4B)
Diseases named in the same sentence as PDE4B in open-access papers (continued):
Sharing a sentence is not in itself a finding about the gene and the disease.
idiopathic pulmonary fibrosis (16 papers, 2021 to 2025). Idiopathic pulmonary fibrosis (IPF) is a nonneoplastic pulmonary disease that is characterized by the formation of scar tissue within the lungs in the absence of any known cause. "Recently, two clinical trials have demonstrated the efficacy of nerandomilast (a specific PDE-4B inhibitor) in idiopathic pulmonary fibrosis (IPF) and progressive pulmonary fibrosis (PPF)." (PMID 41304973, 2025). "Phase I and II clinical trials treating patients with idiopathic pulmonary fibrosis using a novel PDE4B inhibitor, BI 1015550, have shown promising results." (PMID 39691395, 2024). "A clinical trial from New England in 2022 reported the efficacy and safety of PDE4B inhibitor (BI 1015550) in patients with idiopathic pulmonary fibrosis (IPF)." (PMID 38915460, 2024). "In conclusion, pre-clinical and early-phase clinical evidence supports the rationale for targeting PDE4B in pulmonary fibrosis." (PMID 36813290, 2023). "PDE4B upregulation can increase collagen synthesis, which leads to lung fibrosis and liver fibrosis." (PMID 35116054, 2021). "PDE is suggested to contribute to pulmonary fibrosis, and there is a report stating that the PDE4B inhibitor suppress pulmonary fibrosis in mice and HLFs from patients with idiopathic pulmonary fibrosis (IPF) by inhibiting the TGFβ signaling pathway and suppressing cell proliferation via IL-1β." (PMID 39684311, 2024). "In addition to CC-11050, the beneficial effect of another phosphodiesterase 4B inhibitor (BI 1015550) has been tested in patients with idiopathic pulmonary fibrosis (IPF) and other forms of progressive pulmonary fibrosis." (PMID 37854602, 2023). "Phase I and II trials of a novel PDE4B inhibitor in patients with idiopathic pulmonary fibrosis have shown promising results, stabilising pulmonary function measured by change in forced vital capacity from baseline, while maintaining an acceptable safety profile." (PMID 36813290, 2023). "Preferential inhibition of PDE4B may maintain efficacy in treating pulmonary fibrosis whilst avoiding certain adverse events." (PMID 35517783, 2022). "In addition, PDE4B shows higher expression levels in the lung compared with PDE4D and has been implicated in the development of pulmonary fibrosis, whereas PDE4D expression is elevated in the liver under pathological conditions, as shown in this study, thereby promoting liver fibrosis." (PMID 41196648, 2025). "BI 1015550, a phosphodiesterase 4B (PDE4B) inhibitor developed by Boehringer Ingelheim, is currently undergoing clinical trials for idiopathic pulmonary fibrosis (IPF) and progressive pulmonary fibrosis (PPF)." (PMID 40142089, 2025).
Anxiety (11 papers, 2015 to 2026). Intense feelings of nervousness, tension, or panic often arise in response to interpersonal stresses. "Additional genome-wide association data found that cAMP-specific 3′,5′-cyclic phosphodiesterase 4B (PDE4B) enzyme gene variants are associated with anxiety and stress-related disorders." (PMID 33466814, 2021). "It has been reported that changes in PDE4B concentration are associated with depression and anxiety-like behaviors, while PDE4A may play a neuroprotective role by modulating neuroinflammation." (PMID 36979232, 2023). "When compared to wild-type (WT) mice, PDE4A KO or PDE4B KO mice proved anxiety characteristics along with higher corticosterone levels, while PDE4B KO mice also showed increased long-term depression." (PMID 41602587, 2026). "In males, ZEM12.5 decreased anhedonia- and anxiety-like behavior, decreased cortical and hippocampal PDE4B, and increased plasma interleukin-10." (PMID 40643548, 2025). "Male UCMS-exposed rats present with anxiety and anhedonia, as well as deficits in serotonergic and dopaminergic processes, and neuro-inflammation (increased PDE4B)." (PMID 40643548, 2025). "There is evidence of PDE4B involvement in the regulation of affective disorders, anxiety and depression." (PMID 31663033, 2019). "PDE4B expression has been found in the amygdaloid body, pituitary gland and the anterior cortex, which are key regions responsible to anxiety-related behavior and response to stress." (PMID 31663033, 2019). "Our findings establish specific inhibition of PDE4B as apromising therapeutic approach for pathology affecting memory, anxiety, and fearmemory." (PMID 26272049, 2016). "Our data establish specific inhibition of PDE4B as apromising therapeutic approach for disorders of memory and anxiety." (PMID 26272049, 2016). "Our data establish specific inhibition of PDE4B as a promisingtherapeutic approach for disorders of cognition and anxiety, and a putative targetfor pathological fear memory." (PMID 26272049, 2016). "Although poorly tolerated, non-subtype-selective PDE4 inhibitors have the potentialto improve cognitive function, and several lines of evidence suggest that PDE4B maybe a well-tolerated target for anxiety and cognitive enhancement." (PMID 26272049, 2016). "Additionally, and regarding biomarkers related to MDD or anxiety, UCMS-exposed male rats showed a significant increase in hippocampal PDE4B and large effect size changes in cortical 5-HT (decreased) and DOPAC (increased), whilst these were unaltered in their female counterparts." (PMID 40643548, 2025). "In addition, PDE4B expression levels were significantly negatively correlated with trait anxiety (r = −0.38, p = 0.008), but not with state anxiety (p = 0.09) or depressive symptoms (p = 0.11) in the total human sample." (PMID 38409596, 2024). "PDE4D inhibition by D159687, on the other hand, did not induce any behavioral changes in mouse models of depression or anxiety, but improved cognition in the mouse NOR test, whereas as the PDE4B inhibitor had no procognitive benefit in healthy adult mice." (PMID 28054669, 2017).
colorectal cancer (9 papers, 2016 to 2024). A primary or metastatic malignant neoplasm that affects the colon or rectum. "Although rarely mutated in human colorectal cancers, the level of PDE4B protein is reduced in frank colon cancer—possibly through an epigenetic mechanism." (PMID 30188895, 2018). "For the human, the emergent resources of molecular data for colorectal cancer in patients enables an assessment of the mutational and expression status of the PDE4B gene in frank human colon cancer." (PMID 30188895, 2018). "In interrogation of the Dana Farber Cancer Institute (DFCI) dataset, PDE4B mutations are reported in only 9 of 619 colorectal cancers (1.5%)." (PMID 30188895, 2018). "Increased PDE4B expression correlates with relapsed colorectal cancer cell lines, suggesting its potential as a prognostic molecular marker in CRC." (PMID 39202484, 2024). "While some researchers found that inhibition of another PDE isoform, PDE4B, suppressed colorectal cancer cell proliferation and survival." (PMID 36611861, 2022). "PDE4B promotes cancer progression in diffuse large B-cell lymphoma, colorectal cancer, breast cancer, lymphoid carcinoma and liver cancer, whereas in prostate cancer, down-regulation of PDE4B contributes to the occurrence and development of prostate cancer." (PMID 36278172, 2022). "In conclusion, it is necessary to pay attention to the regulatory role played by elevated transcriptional levels of PDE4B in chronic inflammation of the colorectum and colorectal cancer." (PMID 36278172, 2022). "Rolipram (Rol) was reported to be an effective PDE4B inhibitor, which exerted important tumor suppressive effects by inhibiting the PDE4B/mTOR/Myc axis in colorectal cancer." (PMID 34977026, 2021). "Previous study has demonstrated that rolipram was an effective PDE4B inhibitor, which exerted important tumor suppressive effects by inhibiting the PDE4B/mTOR/Myc axis in colorectal cancer." (PMID 34977026, 2021). "Specifically, the Human Protein Atlas reports that 8 out of 12 human colorectal cancers demonstrate reduced intensity of immunostaining for PDE4B antigen in the epithelial component of these cancers, compared to samples from the normal colon and rectum." (PMID 30188895, 2018). "If a predisposition of reduced PDE4B activity in colonic mucosa from colorectal neoplasia patients is substantiated further, this subtype could be a potential novel early diagnostic risk marker and may even be a target for future medical preventive treatment of colorectal cancer." (PMID 27927168, 2016). "Further, intestinal tumorigenesis has a known inflammatory component, perhaps involving PDE4B function On these bases, inactivating the PDE4B function in a colorectal cancer model of inflammation would be expected to attenuate or eliminate the enhancement of colonic adenomagenesis by inflammation." (PMID 30188895, 2018). "Interestingly, 40% of those cancers with mutant PDE4B also possess mutations in the BRAF gene, in contrast to an incidence of only 8–10% BRAF-mutant carriers in the entire colorectal cancer population." (PMID 30188895, 2018). "Similarly, PDE4B was shown to modulate colorectal cancer growth through mTOR." (PMID 37427586, 2023). "PDE4B modulates the expression of MYC that leads to low intracellular cAMP levels, activates AKT/mTOR signaling, and promotes cell survival in colorectal cancer." (PMID 36874096, 2023).
depression (9 papers, 2015 to 2026). "DISC1 and PDE4B may also be important in the development of depression caused by chronic stress." (PMID 26388333, 2015). "There are several lines of evidence supporting a critical role of PDE4B in the etiology of depression." (PMID 28054669, 2017). "Although some studies have shown that exercise can improve the inflammatory response and reduce the depression-like behavior of aging rats; however, MIIT did not significantly alter PDE4A/PDE4B expression in this study, so it may not have been through the PDE4A/PDE4B pathway." (PMID 36979232, 2023).
mental disorder (9 papers, 2015 to 2025). A disease that has its basis in the disruption of mental process. "To examine the effect of PDE4B variation on behaviors relevant to mental disorders, we studied male Pde4bM220T mice that carry a PDE4B variant (M220T), which is also present in humans." (PMID 39256048, 2024). "To examine the effects of PDE4B variation on phenotypes with translational relevance to psychiatric disorders, we focused on PDE4B missense variant M220T, which is present in the human genome as rare coding variant rs775201287." (PMID 39256048, 2024). "To examine the effect of PDE4B variation on phenotypes with translational relevance to psychiatric disorders, we tested mice that replicate human missense variant M220T (rs775201287; 1-66332532-T-C) located in UCR2." (PMID 39256048, 2024). "PDE4B gene polymorphism has been shown to be associated with some mental disorders including panic disorder." (PMID 31663033, 2019). "Interestingly, NCAM1, ASTN2, and PDE4B are known to play important roles in regulating synaptic function and are implicated in human psychiatric disease." (PMID 26694817, 2015). "Additional research highlights a decrease in startle response during pre-pulse inhibition in PDE4B knockout mice, supporting the role of PDE4B in psychiatric diseases." (PMID 39936956, 2025). "Human genetic studies have associated variants in the PDE4B gene, encoding the phosphodiesterase-4B (PDE4B) enzyme, with increased risk for post-traumatic stress disorder (PTSD) and other mental disorders that often occur with it." (PMID 39256048, 2024). "In summation, GWASs have associated variants in PDE4B with PTSD and other psychiatric disorders comorbid with it, but the pathophysiological mechanisms of genetic risk involving PDE4B are poorly understood." (PMID 39256048, 2024). "We have elucidated the connection between DISC1 and DISC1 pathway proteins such as NRXN1 and PDE4B to viral infection as well as to mental disorders." (PMID 35444632, 2022). "Collectively, these data indicate that dysregulation of the PDE4B/DISC1interaction with NDE1/NDEL1/LIS1 complex induces the psychiatric disorder phenotype." (PMID 32438615, 2020). "Changes in the PDE4B gene expression contributes to the change in intracellular cAMP concentrations, which correlates with various psychiatric disorders." (PMID 31663033, 2019). "Several other genes that are dysregulated in mental disorders, such as DISC1, phosphodiesterase 4B (PDE4B), and neurexin-1 (NRXN1), could also be impacted by SARS-CoV-2 infection and contribute to neurotropism and inflammation in the CNS." (PMID 35444632, 2022).
bipolar disorder (8 papers, 2009 to 2023). A disorder of the brain that causes unusual shifts in mood, energy, activity levels and the ability to carry out day-to-day tasks. "Interestingly, the PDE3 inhibitor, dipyridamole, also targets PDE4B and has been investigated therapeutically for bipolar disorders." (PMID 37500481, 2023).
diffuse large B-cell lymphoma (8 papers, 2013 to 2025). "To further test the allele-specific regulation of PDE4B expression by the SNP rs12142375 in B cells, we performed an eQTL analysis using the TCGA diffuse large B-cell lymphoma data." (PMID 29061142, 2017). "PDE4B, a main hydrolyzer of cAMP in B cells, promotes diffuse large B-cell lymphoma cell survival and drug resistance by downregulation of cAMP signaling." (PMID 38233872, 2024). "Previous studies reported that PDE4B expression was increased in diffuse large B-cell lymphoma and non-small cell lung cancer, but was downregulated in prostate cancer." (PMID 34977026, 2021). "cAMP signaling can also be negatively regulated by phosphodiesterase 4B (PDE4B) that is frequently overexpressed in diffuse large B-cell lymphoma (DLBCL)." (PMID 23431463, 2013). "PDE4B is overexpressed in diffuse large B-cell lymphoma and prevents cAMP-induced apoptosis." (PMID 38233872, 2024). "Interestingly, high PDE4B expression is a marker for fatal outcome of diffuse large B-cell lymphoma (DLBCL)." (PMID 35163131, 2022). "Interestingly, the function of PDE4B is cancer-type dependent, i.e., PDE4B overexpression increases malignancy in diffuse large B-cell lymphoma and non-small cell lung cancer, while its underexpression contributes to prostate cancer progression." (PMID 34977026, 2021). "Hence, PDE4B inhibitors may have tumor suppressive effects in diffuse large B-cell lymphoma." (PMID 38233872, 2024). "In addition, the anti-angiogenesis role of Roflumilast in diffuse large B-cell lymphoma (DLBCL) was also reported, PDE4B repressed cAMP to activate PI3K/AKT signals to up-modulate VEGF secretion and Roflumilast could decreased the microvessel density in lymphoma-bearing mice." (PMID 29348829, 2017).
prostate carcinoma (7 papers, 2015 to 2025). A carcinoma that arises from epithelial cells of the prostate gland. "PDE4B expression was also decreased in castration-resistant prostate cancer and advanced prostate cancer." (PMID 38514754, 2024). "Other work evaluating PDE4B isoforms in prostate cancer, observed that PDE4B was down-regulated and the PKA signalling pathway was activated in a castration-resistant LNCaP cell line." (PMID 37830741, 2023). "The PDE4B/PKA signaling pathway contributes to androgen-dependent prostate cancer progression to PC." (PMID 36278172, 2022). "Recent reports of PDE4B knockdown following oxidative stress challenge have also been shown to promote growth of castration-resistant prostate cancer cells." (PMID 25680530, 2015). "This study demonstrates that PDE4B may perform a tumor suppressor role in advanced prostate cancer, but further studies are needed to confirm this role." (PMID 40129976, 2025). "However, the role of PDE4B in prostate cancer appears to differ from that in UBC." (PMID 40129976, 2025).
Alzheimer disease (6 papers, 2020 to 2025). A progressive, neurodegenerative disease characterized by loss of function and death of nerve cells in several areas of the brain leading to loss of cognitive function such as memory and language. "Meta-analysis of genome-wide association study data has implicated PDE4B in the pathogenesis of Alzheimer’s disease (AD), the leading cause of senile dementia." (PMID 38521860, 2024). "Microglia activity can drive excessive synaptic loss during the prodromal phase of Alzheimer’s disease (AD) and is associated with lowered cyclic adenosine monophosphate (cAMP) due to cAMP phosphodiesterase 4B (PDE4B)." (PMID 38920631, 2024). "In addition, Alzheimer’s disease (AD) model mice, which are deficient in PDE4B, show decreased TNFα expression in response to inflammatory stimuli." (PMID 32438615, 2020).
asthma (6 papers, 2011 to 2024). "Specifically, the inhibitory effect of nobiletin on PDE4B and the relief of asthma symptoms via activation of the downstream cAMP-PKA-CREB signaling pathway were investigated in depth." (PMID 39408735, 2024). "In conclusion, our study provides evidence for the activity of nobiletin in improving asthma symptoms by targeting PDE4B and subsequently activating the cAMP-PKA-CREB signaling pathway." (PMID 39408735, 2024). "We found that ADCY2, PDE4B, DNAH5 and KIF3A were again associated with asthma (p<0.05) at the gene level." (PMID 21912604, 2011). "Finally, siRNA tests provided further evidence for the dependence of PDE4B inhibition by nobiletin in exerting its anti-asthma effect." (PMID 39408735, 2024). "Using our approach, we identified five novel genes that had not been previously implicated in asthma and a sixth gene (PDE4B) that was recently linked to asthma." (PMID 21912604, 2011). "Our investigation revealed that six of these genes (PDE4B, SPRR2B, ADCY2, KIF3A, DNAH5, and PLAU) were located in chromosomal regions that had been previously linked to asthma or other allergic disease phenotypes and had been shown to be regulated during allergic inflammation." (PMID 21912604, 2011). "Imputed SNPs within PDE4B not previously genotyped were also significantly associated with asthma." (PMID 21912604, 2011). "These four pathways included the asthma-related cAMP signaling pathway as well as two possible targets, PDE4D and PDE4B, members of phosphodiesterase (PDE) family of enzymes, which are key in regulating cAMP levels." (PMID 32508648, 2020). "A recent large-scale EWAS on blood identified differentially methylated novel genes including multiple drug target genes, PDE4B and PPARG in atopic asthma, and PDE4B and AZU1 in nonatopic asthma." (PMID 35055381, 2022).
chronic obstructive pulmonary disease (6 papers, 2018 to 2024). A chronic and progressive lung disorder characterized by the loss of elasticity of the bronchial tree and the air sacs, destruction of the air sacs wall, thickening of the bronchial wall, and mucous accumulation in the bronchial tree. "The therapeutic potential of PDE4 inhibition in diseases such as chronic obstructive pulmonary disease (COPD), cystic fibrosis and asthma, has long been appreciated, with PDE4B up-regulation in airway epithelial cells being implicated in COPD pathogenesis." (PMID 29593534, 2018). "For example, in chronic obstructive pulmonary disease, the inhibition of PDE4B may result in a reduction of neutrophilic inflammation and mucus hypersecretion, both of which are characteristic features of the disease." (PMID 39691395, 2024). "Taken together, our data suggest that dexamethasone may help attenuate inflammation and tolerance through suppressing the PDE4B expression in chronic obstructive pulmonary disease (COPD) patients using roflumilast." (PMID 30413022, 2018). "Moreover, it has recently been identified that Cβ and not Cα is necessary for inducing expression of PDE4B, a target for treatment of severe chronic obstructive pulmonary disease (COPD)." (PMID 30258407, 2018).